TUBB2B (tubulin beta 2B class IIb)
Diseases named in the same sentence as TUBB2B in open-access papers (continued):
Sharing a sentence is not in itself a finding about the gene and the disease.
tumor (16 papers, 2011 to 2025). "TUBB2B is a novel TNBC gene that plays a key role in promoting tumor cell survival and brain metastatic colonization, and can be targeted by siRNA-AuNPs as a treatment strategy." (PMID 39962586, 2025). "In the tumor maintenance model, HCC1806 cells with tet-on TUBB2B shRNA were implanted orthotopically to generate tumor-bearing mice, followed by dox treatment to induce gene knockdown." (PMID 39962586, 2025). "Using RNAscope in situ hybridization, we not only validated the high expression of TUBB2B in 13% of TNBC primary tumor cases, but also observed high levels of TUBB2B in 57% of TNBC brain metastasis cases." (PMID 39962586, 2025). "TUBB2B knock-down significantly reduced tumor growth rate, while over-expression TUBB2B increased the tumor growth rate resulting in bigger and heavier tumors." (PMID 36872411, 2023). "Deletion of TUBB2B in hepatocytes inhibits proliferation and promotes tumor cell apoptosis, while over-expression of TUBB2B has the opposite function." (PMID 36872411, 2023). "PER1 can promote cell apoptosis and expression of TNF-α, IL-6, and programmed death 1 (PD-1)/PD-L1, and inhibit tumor invasion and TUBB2B gene expression." (PMID 34220965, 2021). "The α-tubulin isoform TUBA8 and the β-tubulin isoform TUBB2B had respectively the highest and the lowest expression levels in the four tumor subtypes." (PMID 30126203, 2018). "TUBB2B silencing in the tumor-bearing mice profoundly reduced tumor volume and weight." (PMID 39962586, 2025). "Importantly, our data showed that the intravenous administration of TUBB2B siRNA-AuNPs to mice resulted in a significant inhibition of tumor growth and brain metastatic colonization, demonstrating the preclinical efficacy of targeting TUBB2B for TNBC." (PMID 39962586, 2025). "Silencing TUBB2B induces tumor cell death and inhibits the outgrowth of brain metastasis." (PMID 39962586, 2025). "Importantly, these promoting effects of astrocytes on TNBC cells were abrogated by TUBB2B depletion in tumor cells." (PMID 39962586, 2025). "We also examined the role of eEF1A1 in mediating TUBB2B-promoting tumor growth in vivo, and showed that overexpression of eEF1A1 could partially rescue the tumor growth in TUBB2B-depleted cells." (PMID 39962586, 2025). "The GSEA analysis revealed that most of the enriched pathways were correlated with lipid metabolism, suggesting that TUBB2B expression may affect lipid metabolism in tumor development." (PMID 36872411, 2023). "Expression of TUBB2B (tubulin β2B), the second most significant upregulated gene in this analysis, coincided with expression of the small‐cell/neuroendocrine differentiation genes, and IHC showed that it was expressed by tumour cells." (PMID 28195647, 2017). "TUBB2B (tubulin beta 2B class IIb) may have important roles in tumor progression and chemoresistance." (PMID 27259239, 2016). "In line with its neural-related functions, TUBB2B overexpression in TNBC cells activates astrocytes, which in turn upregulate TUBB2B in tumor cells." (PMID 39962586, 2025). "TUBB2B regulated the expression of TNF-a, IL-6, and PD-1/PD-L1 through the inhibit tumor invasion gene PER1." (PMID 37719786, 2023). "We also found that TUBB2B modulates cholesterol metabolism via targeting CYP27A1, an enzyme responsible for the conversion of cholesterol to 27-hydroxycholesterol, to promote tumor progression." (PMID 36872411, 2023). "We found that tumor tissues express significantly higher levels of TUBB and TUBB3 and significantly lower levels of TUBB2B, TUBB6, and TUBB7P pseudogene." (PMID 30126203, 2018). "One‐half of these tumours expressed markers that are typical for neuroendocrine differentiation, e.g. SYP and ENO2, and, more robustly, TUBB2B." (PMID 28195647, 2017).
tumor (continued). "In the HPA data, compared with normal tissues, the expression of PKMYT1, ETF1, RECQL4, TUBB2B, and CDC6 in tumor tissues was remarkably upregulated, while the expression of TFRC and PITX1 was significantly downregulated (,ECT2, BUBB1B, and COCH were not included)." (PMID 33869220, 2021). "Analyzing expression profile of BC tumors and tumor-adjacent normal breast tissues showed upregulation of TUBA1A, TUBA1C, TUBB and TUBB3 and downregulation of TUBB2A, TUBB2B, TUBB6, TUBB7P pseudogene, and TUBGCP2 in the tumor tissues compared to the normal breast tissues." (PMID 30126203, 2018). "According to the CPTAC data, the protein expression of PKMYT1, ETF1, ECT2, BUB1B, and RECQL4 in tumor tissues was significantly increased, while the expression of TFRC was significantly reduced, and the expression of COCH and TUBB2B did not change significantly (PITX1 and CDC6 were not included)." (PMID 33869220, 2021).
cancer (9 papers, 2010 to 2025). A tumor composed of atypical neoplastic, often pleomorphic cells that invade other tissues. "In the second family in which MPT21 and two relatives were tested, we found four LP variants (BPIF1, BCORL1, ROPN1, and PRSS3) and four other cancer-related genes (TUBB2B, CFAP54, PSG2, and SIRPB1)." (PMID 39408606, 2024). "Among the β-tubulin isotypes, significant upregulation of TUBB2B was noted in LTED cells compared to parental MCF-7 cells, suggesting the possibility that TUBB2B can play a common biological role in cancer cells." (PMID 37754248, 2023). "Our bioinformatics analysis revealed TUBB2B as a potential cancer driver gene in TNBC." (PMID 39962586, 2025). "Variants in four genes (ROPN1, PRSS3, BPIFB1, and BCORL1) were detected in all individuals from Family 2, while four (TUBB2B, CAFAP54, PSG2, and SIRPB1) were exclusive of the MPT21 index case and her relative with cancer (MPT21.2)." (PMID 39408606, 2024). "Similarly, other additional tubulin isotypes TUBB2B, TUBB8, and TUBA1C, which I observed in first level of our selection steps, were previously reported to involve in nucleation of MT, cancer progression, oocyte maturation, and neuronal abnormalities." (PMID 37466845, 2023).
nervous system disorder (3 papers, 2013 to 2025). A non-neoplastic or neoplastic disorder that affects the brain, spinal cord, or peripheral nerves. "Recently, mutations in neuronal tubulin genes (e.g. TUBA1A, TUBB2B, TUBB3 and TUBA8) have been identified in patients suffering from nervous system disorders, underlining the importance of tubulin isotypes in MT dynamics during brain development and axon guidance." (PMID 26331477, 2015).
kidney disease (2 papers, 2020 to 2022). "TUBB2B mutation leads to tubulin heterodimerization impairment, decreased ability to incorporate into the cytoskeleton, and alteration of microtubule dynamics, with an accelerated rate of depolymerization, which causes renal disease and an increase in the incidence of KIRC." (PMID 32883362, 2020). "TUBB2B alterations can lead to increased incidence of kidney disease and KIRC." (PMID 35860566, 2022).
infection (1 paper, 2019). The state of being infected such as from the introduction of a foreign agent such as serum, vaccine, antigenic substance or organism. "The analysis also identified four tubulin genes (Tubb2A, Tubb2b, Tubb3 and Tubb4B) which have previously been associated with E. coli pathogenesis, to be up-regulated in the asymptomatic (resilient to infection) dataset." (PMID 30709726, 2019).
neurodegenerative disease (1 paper, 2025). A disorder of the central nervous system characterized by gradual and progressive loss of neural tissue and neurologic function. "TUBB2B, encoding tubulin beta 2B, is linked to cortical malformations and microtubule dysfunction, common in neurodegenerative diseases like AD." (PMID 40018519, 2025).
TUBB2B also shares sentences with these, for which no sentence is quoted: hepatocellular carcinoma (3 papers); Intellectual disability (3); neurodevelopmental disorder (3); Pachygyria (3); ptosis (3); epileptic seizures (2); gastric cancer (2); asthenozoospermia (1); astrocytomas (1); band heterotopia (1); bladder tumors (1); central precocious puberty (1); cerebellar agenesis (1); cerebellar ataxia (1); Dystonia (1); esophageal squamous cell carcinoma (1); Exotropia (1); Fibrosis of (1); hay fever (1); hearing loss (1); Infertility (1); melanoma (1); Miller-Dieker syndrome (1); Myoclonus (1); ophthalmoplegia (1); optic nerve hypoplasia (1); pituitary hormone deficiencies (1); schizencephaly (1); Strabismus (1); Tremor (1).
A further 1 disease shares a sentence with TUBB2B in 1 paper.